HRK (harakiri, BCL2 interacting protein)
Description:
Promotes apoptosis.
Synonyms: DP5; HARAKIRI
Tractability: Antibody: UniProt predicts a signal peptide or a membrane-spanning region.
Gene: Protein-coding gene on chromosome 12 (116,856,144 to 116,881,441, reverse strand). Ensembl gene ENSG00000135116.
Subcellular location: Membrane; Mitochondrion
Gene Ontology:
Molecular function: protein binding
Biological process: positive regulation of apoptotic process; positive regulation of protein-containing complex assembly; positive regulation of release of cytochrome c from mitochondria; cellular response to potassium ion starvation; positive regulation of neuron apoptotic process; regulation of apoptotic process
Cellular component: mitochondrion; membrane
Genetic constraint (gnomAD): Loss-of-function variants: 6 observed, 2.14 expected, observed/expected ratio (o/e) 2.81. That is too few expected variants to judge how well the gene tolerates losing a copy. Missense variants: 133 observed, 70.8 expected, observed/expected ratio (o/e) 1.88, 90% interval 1.61 to 1.98. Synonymous variants: 85 observed, 43.1 expected, observed/expected ratio (o/e) 1.97, 90% interval 1.6 to 1.99.
Homologues: Orthologues: chimpanzee HRK (99% identical), rabbit HRK (99% identical), pig HRK (98% identical), mouse Hrk (74% identical), rat Hrk (74% identical).
Diseases named in the same sentence as HRK in open-access papers:
HRK is named in the same sentence as 33 diseases in open-access papers, as found by Europe PMC text mining. Sharing a sentence is not in itself a finding about the gene and the disease. The quoted sentences say what the papers report.
prostate carcinoma (8 papers, 2014 to 2023). A carcinoma that arises from epithelial cells of the prostate gland. "Evidence has shown that the inactivation of HRK in prostate cancer constitutes a critical component in decreased apoptosis of tumour cells, whereas HRK-mediated mitochondrial dysfunction contributes to enhanced apoptosis in human malignancies." (PMID 35804353, 2022). "HRK is expressed in normal tissues but its decreased expression has been reported following promoter methylation in many cancers such as melanoma, prostate cancer and astrocytic tumors." (PMID 27478805, 2016). "Some studies revealed that HRK, as a potential pro-apoptotic gene, may contribute to the development and progression of many human cancers, such as prostate cancers and astrocytic tumors." (PMID 37371530, 2023). "Taken together, our results demonstrated that TRAIL-R2, Gadd45a and HRK may be novel target genes for further study of the mechanism of AT2R-mediated apoptosis in prostate cancer cells." (PMID 24658029, 2014). "We also believe that the combination of AT2R overexpression and TRAIL-R2 downregulation or HRK overexpresssion might be promising as a new gene therapy against human prostate cancers." (PMID 24658029, 2014). "One unknown question that remains undiscovered is the main signaling pathways or factors in apoptosis induced by AT2R, which can be affected by Gadd45a, TRAIL-R2 and HRK in prostate cancer cells." (PMID 24658029, 2014). "HRK gene seems to have an important role in the apoptosis regulation in tumor cells, and its inactivation by methylation could be related to tumorigenesis of prostate cancer." (PMID 35747788, 2022). "Methylation inactivation in tumor suppressors genes, such as MT1M, MT1H, MT1X, and HRK, is responsible for the development of various cancers, such as prostate cancer, liver cancer, colorectal cancer, and gastric cancer, but loss of these genes may be linked with the pathogenesis of BRCA." (PMID 31311202, 2019). "HRK belongs to the BCL-2 protein family, which has been shown to have antitumor effects in prostate cancer." (PMID 36568155, 2022). "In colorectal cancer, gastric cancer and prostate cancer, HRK is often at low or absent expression level." (PMID 36568155, 2022). "Some studies have proved that high apoptotic index in prostate cancer is positively correlated with HRK expression, and it has also been suggested in the literature that HRK plays a key role in the induction of JNK/mitochondria-dependent apoptosis in prostate cancer cells by 2-ME." (PMID 36568155, 2022). "However, there are some questions to be answered such as, the mechanism of the apoptotic pathway from AT2R to HRK was not illustrated and whether or not the HRK could triggers apoptosis in other prostate cancer cells." (PMID 24658029, 2014).
melanoma (5 papers, 2019 to 2024). A malignant, usually aggressive tumor composed of atypical, neoplastic melanocytes. "(but in melanoma, this physical interaction is regulated by hypermethylation of the HRK promoter preventing binding of TFAP2A and synergically with the loss of TFAP2A)." (PMID 37291585, 2023). "Artificial overexpression of HRK by recombinant adenovirus-induced caspase-dependent apoptosis inhibited melanoma cell growth in vitro." (PMID 37371530, 2023). "Elevated HRK leads to apoptosis and promotes the growth, invasion and metastasis of melanoma cells." (PMID 37291585, 2023). "In addition, it was previously reported that HRK is expressed in normal tissue but is decreased in melanoma." (PMID 37371530, 2023). "Genes like FASLG, HRK and SNCA, which were observed to be downregulated, also play role in prevention of mitochondrial damage and apoptosis inhibition in melanoma/medulloblastoma cell lines." (PMID 36845715, 2023).
gastric cancer (4 papers, 2019 to 2023). A primary or metastatic malignant neoplasm involving the stomach. "It has been reported that HRK is deficient in expression in colorectal and gastric cancers." (PMID 36568155, 2022). "In addition, our previous study also demonstrated a strong cytotoxic effect of andrographolide in gastric cancer cell lines by inducing cell death via apoptosis through the induction of proapoptotic proteins, including BCL2L1, EDOG, HRK, and PUMA." (PMID 37958849, 2023). "Knockdown of ARID1A decreased HRK expression without direct binding to the HRK gene in gastric cancer cells." (PMID 34799565, 2021).
glioblastoma (4 papers, 2014 to 2020). The most malignant astrocytic tumor (WHO grade IV). "Additionally, a recent study shows that silencing KDM2B, a H3K36-specific histone demethylase, can cause a de-repression of a pro-apoptotic gene Harakiri (HRK) in glioblastoma multiforme cells." (PMID 35582230, 2020). "HRK inactivation is associated with a low apoptotic index in secondary glioblastomas." (PMID 24658029, 2014). "In this study, we investigated the role of HRK in the most aggressive primary brain tumor, glioblastoma multiforme (GBM)." (PMID 30774992, 2019). "Harakiri (HRK), a BH3-only protein of the Bcl-2 family, has been shown to promote TRAIL-mediated apoptosis in glioblastoma cells." (PMID 31022877, 2019).
breast carcinoma (2 papers, 2020 to 2021). "Overexpression of BAK1 has previously been associated with a favourable prognosis in breast cancer, while BOK, BAK1 and HRK as effectors are inserted into the mitochondrial outer membrane, resulting in MOMP without sequestration by the guardians." (PMID 32419250, 2020). "It has been recently reported that resistance to MCL-1 treatment in a metastatic model of breast cancer could be mediated by BCL-xL; in fact, we validated this observation performing DBP with the HRK peptide, as we observed a synergistic combination when sequentially combining S63845 and A-133." (PMID 34359829, 2021).
colon cancer (2 papers, 2017 to 2019). "We then treated cells with BAD, NOXA, PUMA, BMF, and HRK BH3 peptides, which have variable affinities for anti-apoptotic proteins, and compared the mitochondrial depolarization between parental and 5-FU-resistant colon cancer cells." (PMID 31638265, 2019). "Whereas among the up-regulated genes, there are three pro-apoptosis genes including HRK, TXNIP and DDIT3, which may also helpful to explain how aspirin can induce cellular apoptosis in colon cancer." (PMID 28184026, 2017).
colorectal cancer (2 papers, 2019 to 2022). A primary or metastatic malignant neoplasm that affects the colon or rectum. "It is suggested that HRK downregulation is associated with development and progression of colorectal cancer, making this protein a promising target for blocking or reversing progression of colorectal cancer." (PMID 36568155, 2022). "Highlighting that low-expressed HRK prevents apoptosis as well as promotes the proliferation, invasion and migration of colorectal cancer cells through PI3K/AKT/mTOR signaling pathway." (PMID 36568155, 2022). "According to GSE87211 and GSE39582, we found that the mRNA expression of HRK in colorectal cancer was lower than adjacent normal mucosa." (PMID 36568155, 2022). "In this study, we aimed to investigate the expression level of HRK in colorectal cancer and to demonstrate that the effect of HRK on the biological function of colorectal cancer cells is regulated through the PI3K/AKT/mTOR pathway." (PMID 36568155, 2022). "And for the first time, HRK was shown to promote apoptosis and inhibit proliferation of colorectal cancer cells by inhibiting PI3K/AKT/mTOR signaling pathway." (PMID 36568155, 2022). "In this study, we verified the expression levels of HRK in colorectal cancer tissues by public database search as well as immunohistochemistry." (PMID 36568155, 2022). "The immunohistochemistry (IHC) found that HRK expression was lower in colorectal cancer tissues compared to normal intestinal epithelium." (PMID 36568155, 2022). "This suggests that colorectal cancer patients with lower HRK expression are more likely to occur with distant metastases." (PMID 36568155, 2022). "The data suggest that in colorectal cancer cells, HRK acts as a tumor suppressor gene." (PMID 36568155, 2022). "The expression of HRK was lower in colorectal cancer than that in normal tissues." (PMID 36568155, 2022). "In conclusion, our study found that HRK expression was reduced in colorectal cancer." (PMID 36568155, 2022). "Our study demonstrates that HRK is lowly expressed in colorectal cancer tissues." (PMID 36568155, 2022). "Combined with the previous results, HRK may be a marker to indicate the prognosis of colorectal cancer." (PMID 36568155, 2022).
neuroblastoma (2 papers, 2021). Neuroblastoma (NB) is the most common solid, extracranial childhood tumor. "Therefore, we identified HRK as a novel tumor suppressor in neuroblastoma that is negatively regulated by YAP to prevent therapy induced apoptosis in the in situ TME." (PMID 34572875, 2021). "Therefore, the role for YAP as well as HRK in hypoxia and angiogenesis in neuroblastoma deserve further exploration." (PMID 34572875, 2021). "Therefore, epigenetic modifying agents may have therapeutic potential in the context of HRK upregulation to restore stress-induced apoptosis in neuroblastoma." (PMID 34572875, 2021). "Currently, how YAP regulates HRK expression in neuroblastoma is unknown." (PMID 34572875, 2021). "A recent study showed that Yes-associated protein (YAP)-knockdown increased HRK expression in neuroblastoma, suggesting that YAP is a suppressor of HRK expression." (PMID 34799565, 2021). "We were also able to restore cytotoxic therapy response in vitro in neuroblastoma cells by serum starvation, but apoptosis only occurred when YAP was genetically inhibited to allow for HRK expression and activation in response to serum deprivation and chemotherapy." (PMID 34572875, 2021). "We functionally validated HRK suppression by YAP in neuroblastoma cell lines, showed that HRK is suppressed when YAP is increased in relapsed tumors, and demonstrated that following chemotherapy treatment of PDXs in vivo, YAP expression increases while HRK expression decreases." (PMID 34572875, 2021).
ovarian carcinoma (2 papers, 2019 to 2021). A malignant neoplasm originating from the surface ovarian epithelium. "Under stress conditions, BCL2A1 accumulated and colocalized with mitochondria to suppress intrinsic cell apoptosis by interacting with the BH3-only subfamily BCL2 members HRK/BAD/BID in ovarian cancer cells." (PMID 34572804, 2021). "In the literature, there have been a few studies examining the role of HRK expression in tumors, and these focused on prostate, breast, ovarian cancers, and melanoma." (PMID 30774992, 2019).
cervical cancer (1 paper, 2023). A primary or metastatic malignant neoplasm involving the cervix. "Our study fills a gap in the HRK gene in HeLa cervical cancer cells and provides a theoretical basis for the regulation of mitosis in mitochondria by BCL2 family proteins." (PMID 37371530, 2023). "However, the effect of metformin on HRK gene expression in cervical cancer cells has not been fully elucidated." (PMID 37371530, 2023).
Chronic lymphocytic leukaemia (1 paper, 2016). "Chronic lymphocytic leukaemia cells were sensitive to BIM and BAD peptides but not to HRK or MS-1, consistent with their BCL-2-addiction." (PMID 26954718, 2016).
chronic myeloid leukemia (1 paper, 2023). "The daunorubicin-resistant subcellline (NiWi-Dau) of chronic myeloid leukemia cells K562 has been shown in previous studies to under-express HRK." (PMID 36674465, 2023).
COVID-19 (1 paper, 2022). A disease caused by infection with severe acute respiratory syndrome coronavirus 2. "Also, GADD45G, HRK, and BAK, as proapoptotic proteins, showed a significant increase with severity in COVID-19." (PMID 35573725, 2022).
glioma (1 paper, 2013). A benign or malignant brain and spinal cord tumor that arises from glial cells (astrocytes, oligodendrocytes, ependymal cells). "In support of this notion, the loss of glioma cell survival upon APPL2 knockdown can be rescued either by an excess of netrin‐1, the prosurvival ligand of UNC5B or by simultaneous silencing of HRK." (PMID 22989406, 2013). "We observed that HRK has indeed a proapoptotic activity in both cell lines and that the increase in its level is able to induce death of glioma cells." (PMID 22989406, 2013). "To study the potential involvement of the proapoptotic protein HRK in the regulation of glioma cell survival we overexpressed HRK in LN229 and U87MG cells and measured their viability 3 days later." (PMID 22989406, 2013). "We show that modulation of APPL2 level in glioma cells changes the expression of genes responsible for cell death induction, HRK and UNC5B, suggesting one possible molecular mechanism by which APPL2 may enhance tumor cell growth and apoptosis resistance." (PMID 22989406, 2013). "Cumulatively, these data argue that the endosomal localization of APPL2 is not required for its prosurvival activity and regulation of HRK expression in glioma cells." (PMID 22989406, 2013).
lymphoma (1 paper, 2024). A malignant (clonal) proliferation of B- lymphocytes or T- lymphocytes which involves the lymph nodes, bone marrow and/or extranodal sites. "Of note, epigenetic suppression of HRK has been implicated in the pathogenesis of several human cancers including high-grade lymphomas, and NOXA has been identified as a rheostat for venetoclax sensitivity in different types of blood malignancies." (PMID 38724507, 2024).
viral infection (1 paper, 2012). "Thus, the strong up-regulation of HRK but not Bcl-2 as well as the minor Bcl-xL up-regulation provides evidence that the viral infection was able to trigger apoptosis." (PMID 22238639, 2012).
cancer (21 papers, 2013 to 2025). A tumor composed of atypical neoplastic, often pleomorphic cells that invade other tissues. "This explains the altered response of TIS cancer cells to the HRK peptide and their susceptibility to ABT-263/A1331852, which restores apoptotic competence by disrupting the BCL-xL/BAX interaction." (PMID 41280927, 2025). "HRK inactivation is implicated in tumorigenesis across diverse cancer types, while HRK-expressing tumors demonstrate reduced proliferative capacity, diminished vascularization, and improved survival in murine models." (PMID 41334581, 2025). "HRK is a pro-apoptotic gene associated with several forms of cancer and reported in one GWAS of AD age of onset." (PMID 30279459, 2020). "Loss of HRK expression has been reported in a variety of carcinomas." (PMID 36568155, 2022). "In cancer tissues, HRK was highly expressed in 32.26% (10 of 31) of cases and lowly expressed in 67.74% (21 of 31) (P <0.05)." (PMID 36568155, 2022). "On the contrary, inactivation of HRK expression by promoter hypermethylation contributes to the development and progression of various human cancers." (PMID 23776502, 2013). "Early studies found that low expression of HRK promotes the development and progression of cancer." (PMID 36568155, 2022). "We found that the expression level of HRK is heterogeneous in pan-cancer." (PMID 36568155, 2022). "Since suppression of HRK occurs in cancers, it may play an important role in the development and progression of human tumors." (PMID 27478805, 2016). "BH3 profiling with sensitizing peptides that preferentially disrupt BCL-xL interactions (e.g., HRK) functionally confirmed the strong dependence on BCL-xL as a dominant survival factor that maintains mitochondrial integrity even in minimally primed TIS cancer cells." (PMID 41280927, 2025). "Therefore, HRK might be used as a target for demethylation therapy to stimulate apoptosis in cancer cells." (PMID 27478805, 2016). "Finally, through gene expression analysis, we identified signaling molecules that might contribute toward TRAIL and MSC-TRAIL resistance in CD133+ CSCs, and uncovered NFKB1, BAG3, MCL1, GADD45A, and HRK as potential anti-cancer genes that could increase sensitivity of NSCLC to MSC-TRAIL therapy." (PMID 31466290, 2019). "Like vincristine, we could detect an increase in priming with BAD, HRK, and MS1 BH3 peptides in CW9019 cells indicating that cancer cells also acquired resistance to doxorubicin treatment through BCL-xL and MCL-1." (PMID 32801295, 2020). "Although the HRK methylation status has been extensively studied in cancers, there are no reports in this regard in MDS." (PMID 27478805, 2016). "Despite its potential significance, the role of HRK function has not been well-defined in cancer." (PMID 36568155, 2022). "However, the regulatory role of HRK in the apoptosis of cancer cells has not been studied before." (PMID 30774992, 2019).